RNY1P4 (RNY1 pseudogene 4)
Gene: Miscellaneous RNA gene on chromosome 13 (32,763,438 to 32,763,552, reverse strand). Ensembl gene ENSG00000207325.
Homologues: Orthologues: chimpanzee Y_RNA (97% identical), macaque Y_RNA (92% identical). Paralogues in human: Y_RNA (80% identical), Y_RNA (78% identical), RNY1 (77% identical), Y_RNA (77% identical), RNY1P11 (76% identical), Y_RNA (76% identical), RNY1P1 (75% identical), RNY1P7 (75% identical), Y_RNA (75% identical), RNY1P5 (74% identical), Y_RNA (74% identical), Y_RNA (73% identical), and 87 more.